PRKAR1A (protein kinase cAMP-dependent type I regulatory subunit alpha)
Diseases named in the same sentence as PRKAR1A in open-access papers (continued):
Sharing a sentence is not in itself a finding about the gene and the disease.
adrenocortical carcinoma (3 papers, 2018 to 2025). "PRKAR1A loss of function mutations were rarer, including both inactivating mutations (0.2–5.3%) and deep deletions (0.4–4%), that were predominantly detected in adrenocortical carcinoma." (PMID 36692000, 2023). "As a prominent example, in the transcriptome of an adrenocortical carcinoma (ACC) sample, we detected an SSCV in a deep intronic region affecting PRKAR1A, a gene linked to ACC tumorigenesis." (PMID 39788962, 2025). "(G) Summary gene set enrichment analysis (GSEA) of PRKACA amplified/mutant and PRKAR1A inactivated adrenocortical carcinoma or ovarian serous carcinoma vs. WT from TCGA." (PMID 36692000, 2023).
colon carcinoma (3 papers, 2012 to 2023). "A second SNP, rs8905, within the 3’ UTR of PRKAR1A was associated with over a twofold increased risk of colon cancer (ORGG 2.31 95% CI 1.11, 4.77)." (PMID 26630397, 2015). "The PRKAR1A down-regulation also linked to multidrug-resistant (MDR) in colon carcinoma cells." (PMID 23122428, 2012).
depression (3 papers, 2016 to 2024). "With higher basal and stimulated PKA activity levels in the basolateral amygdala, Prkar1α+/− mice exhibited anxiety- and depression-like behaviors, suggesting that an increase in PKA activity may be associated with an increased risk for anxiety." (PMID 26747511, 2016). "There were five overlapping hub genes in the two datasets including CASP1, IRS2, PRKAR1A, SNAP23, and VTI1A, which were identified as the key genes in the comorbidity of PCOS and depression." (PMID 38674428, 2024). "Prior studies in our lab showed that transgenic mice with a downregulated Prkar1a gene (tTA/X2AS, antisense transgene) exhibited behavioral abnormalities, including anxiety and depression." (PMID 27445986, 2016). "For the PRKAR1A gene, a negative association was detected between rs11077579 and the patients with PCOS and depression in the co-dominant genetic model (OR = 0.38, 95% CI: 0.14–0.98)." (PMID 38674428, 2024). "Consequently, it is speculated that PRKAR1A mediates PKA-dependent snapin to work together with SNAP23 in the comorbidity of PCOS and depression." (PMID 38674428, 2024).
hyperthyroidism (3 papers, 2022 to 2024). Overactivity of the thyroid gland resulting in overproduction of thyroid hormone and increased metabolic rate. "Demonstrates that thyroid-specific ablation of PRKAR1A leads to hyperthyroidism and follicular thyroid cancer." (PMID 38074042, 2023).
osteosarcoma (3 papers, 2011 to 2022). A usually aggressive malignant bone-forming mesenchymal neoplasm, predominantly affecting adolescents and young adults. "Overactive cAMP/PKA signaling caused by Prkar1a gene deletion in aggressive osteosarcoma was responsible for the high expression of RANKL." (PMID 36199692, 2022). "A correlation between human osteosarcoma expression of Prkar1α and response to chemotherapy was also discussed in the same paper but rendered somewhat equivocal results." (PMID 21403899, 2011). "Prkar1α may be a critical tumor suppressor for this particular model and perhaps a subset of osteosarcomas, but not critical overall." (PMID 21403899, 2011).
ovarian carcinoma (3 papers, 2018 to 2023). A malignant neoplasm originating from the surface ovarian epithelium. "While MOB1A and CCDC6 were significantly over-expressed in ovarian cancer samples, expression of these genes, as well as of TUBB, PRKAR1A, and SOCS3 appeared to be expressed at high levels in multiple healthy tissue sites." (PMID 36943460, 2023).
Anxiety (2 papers, 2016). Intense feelings of nervousness, tension, or panic often arise in response to interpersonal stresses. "We hypothesized that a transgenic mouse model with downregulation of Prkar1a would provide a research tool to evaluate the effect of altered PKA expression on anxiety-like behaviors." (PMID 27445986, 2016). "The phenotype of Prkaca+/− mice was characterized by attenuation but not elimination of the anxiety phenotype noted in Prkar1a heterozygote mice." (PMID 27445986, 2016). "Compared with WT mice, Prkar1a+/− mice had higher basal and stimulated (cAMP) PKA activity levels in the central and basolateral amygdala, brain areas known to have a critical role in the processing of sensory information related to anxiety and emotion as well as regulation of arousal level." (PMID 27445986, 2016).
brain tumor (2 papers, 2019 to 2024). "Quantitative assessment of mRNA BDKRB1, PRKAR1A, MAP2K, and EGFR in patients with brain tumors may hold diagnostic and therapeutic significance." (PMID 38254732, 2024).
endocrine neoplasia (2 papers, 2016 to 2017). "Loss of PRKAR1A was frequently observed in endocrine neoplasia and stromal cell tumors." (PMID 27995993, 2016).
Hereditary pancreatitis (2 papers, 2012). "Another group of five uORFs associated with diseases have been tested recently using reporter assays; they include gonadal dysgenesis (SRY), Van der Woude syndrome (IRF6), Carney Complex Type 1 (PRKAR1A), Hereditary pancreatitis (SPINK1), and Thalassaemia-β (HBB)." (PMID 22693426, 2012).
hypercortisolism (2 papers, 2016 to 2026). "Human ACBD3 is highly expressed in steroidogenic tissues, where it follows the pattern of PRKAR1A expression, suggesting that it participates in PRKAR1A-mediated tumorigenesis and hypercortisolism." (PMID 27375556, 2016).
myopia (2 papers, 2016 to 2021). "Among the mRNAs targeted by differentially expressed miRNAs, there were several (Prkar1a, Rims2, Map2, Gabarapl1, Htr7, Add3, Erc1, Nlgn1) which were involved in synapse formation and function suggesting that synaptic function was one of the biological processes affected in form-deprivation myopia." (PMID 27622715, 2016).
somatotroph tumors (2 papers, 2010 to 2022). "The cyclic AMP pathway is important for somatotroph pathogenesis as its upregulation via somatic gsp mutations (MIM♯ 139320) or via PRKAR1A (MIM♯ 188830) mutations lead to somatotropinomas [Horvath and Stratakis, 2008]." (PMID 20506337, 2010). "While somatic mutations of GNAS are the most prevalent cause of somatotroph tumors, germline mutations in various genes (AIP, PRKAR1A, GPR101, GNAS, MEN1, CDKN1B, SDHx, MAX) are also known as the cause of somatotroph tumors." (PMID 36010855, 2022).
ACTHomas (1 paper, 2020). "Somatic mutations in the MEN1, PRKAR1A, and GNAS1 genes have also been reported in ACTHomas." (PMID 33266265, 2020).
adrenal Cushing syndrome (1 paper, 2018). "Germline or sporadic inactivating PRKAR1A, PDE11A, and PDE8B mutations have also been described in i-PPNAD causing adrenal Cushing syndrome." (PMID 29594118, 2018).
adrenal hyperplasia (1 paper, 2015). "Mice bearing a transgene expressing an anti-sense Prkar1a construct (AS-Prkar1a) developed more tumors than the Prkar1a+/− mice, including adrenal hyperplasia, histiocytic sarcomas (HS) and lymphomas." (PMID 26608815, 2015).
anemia (1 paper, 2017). A reduction in the number of red blood cells, the amount of hemoglobin, and/or the volume of packed red blood cells. "PRKAR1A inactivating mutations are associated with metabolic syndromes in which anemia is prevalent." (PMID 28553927, 2017).
angiomyxoma (1 paper, 2023). A benign soft tissue neoplasm characterized by the presence of neoplastic spindle and stellate cells, and vascular proliferation in a myxoid stroma. "Moreover, in non-syndromic superficial angiomyxoma, the absent or reduced expression of cAMP-dependent protein kinase type I-alpha regulatory subunit (PRKAR1A) has been observed." (PMID 37830671, 2023).
atherosclerosis (1 paper, 2024). A disease characterized by the build-up of fatty material and calcium deposition in the arterial wall resulting in partial or complete occlusion of the arterial lumen. "The five key genes related to three pathways included the SNARE interactions in the vesicular transport pathway (SNAP23, VTI1A), the insulin signaling pathway (IRS2, PRKAR1A), and lipid and atherosclerosis (CASP1)." (PMID 38674428, 2024).
craniosynostosis (1 paper, 2023). Craniosynostosis is defined as the premature fusion of one or more cranial sutures leading to secondary distortion of skull shape resulting in skull deformities with a variable presentation. "Among the four novel loci (ZIC1, PRKAR1A, AZIN1/ATP6V1C1, GLRX3), there are factors implicated in intramembranous ossification and as we show, inherent to craniosynostosis processes." (PMID 37402774, 2023). "Functional follow-up with zebrafish models provided robust evidence for the implication of PRKAR1A, ZIC1 and ATP6V1C1 in the mineralization of the skull and pointed to a conceivable role of these genes in craniosynostosis." (PMID 37402774, 2023).
E. coli infection (1 paper, 2020). "Thus, EPS pretreatment can reduce the overexpression of PRKAR1A and CAMK2G, which are activated in E. coli infection." (PMID 32234079, 2020).
Hyperglycemia (1 paper, 2020). An increased concentration of glucose in the blood. "Significant hyperglycemia was observed in both fasting and fed states compared to control starting at 10 days and enduring until 28 days post-injection in wildtype mice treated with siPrkar1a sequences in a manner correlating with the potency of Prkar1a reduction." (PMID 32735622, 2020).
hyperinsulinemic hypoglycemia (1 paper, 2020). An inherited autosomal recessive syndrome characterized by the disorganized formation of new islets in the pancreas and congenital hyperinsulinism. "However, the ability of Prkar1a reduction to resolve fasting hypoglycemia in the Sur1-/- hyperinsulinism model exposes new possible therapeutic targets in the liver, PKA and glucagon signaling pathways in the treatment of hyperinsulinemic hypoglycemia." (PMID 32735622, 2020).
hyperinsulinism (1 paper, 2020). Abnormally high levels of insulin in the blood. "Examination of the Sur1-/- hyperinsulinism mouse model in the context of Prkar1a reduction, identified a distinct increase in not only fasting plasma glucose levels, but also a significant decrease in fasting insulin/glucose levels as well." (PMID 32735622, 2020).
Hypoglycemia (1 paper, 2020). A decreased concentration of glucose in the blood. "Loss of Prkar1a in the Sur1-/- mouse model of KATP hyperinsulinism significantly attenuated fasting induced hypoglycemia, decreased the insulin/glucose ratio, and also increased the hepatic expression of Kiss1 by more than 10-fold." (PMID 32735622, 2020). "Given the ability of disinhibited PKA to increase plasma glucose levels, we wanted to evaluate the effect of Prkar1a reduction in the liver on hypoglycemia caused by hyperinsulinemic conditions." (PMID 32735622, 2020).
Intellectual disability (1 paper, 2017). "In “CNC plus,” a 2.3-Mb deletion of 17q24.2-q24.3 covering the PRKAR1A gene has been associated with posterior laryngeal cleft, growth retardation, microcephaly, moderate intellectual disability, and numerous freckles/lentigines." (PMID 28973408, 2017).
lactotroph adenomas (1 paper, 2025). "Located on 17q24.2, protein kinase cAMP-dependent type I regulatory subunit alpha (PRKAR1A) is also related to the tumorigenesis of somatotroph and lactotroph adenomas, and it has been stated that its loss enhances protein kinase A (PKA) signaling." (PMID 40299639, 2025).
Lymphadenopathy (1 paper, 2015). Enlargement (swelling) of a lymph node. "Prkar1a+/−, Prkar2a+/−, Prkar2a−/−, Prkar2b+/− and wild type (WT) mice were necropsied when they developed splenomegaly, lymphadenopathy (at any age) or when moribund between 5 and 25 months of age." (PMID 26608815, 2015).
lymphoma (1 paper, 2015). A malignant (clonal) proliferation of B- lymphocytes or T- lymphocytes which involves the lymph nodes, bone marrow and/or extranodal sites. "Lymphomas or HS have not been reported in patients with CNC but were among the tumors found relatively rarely in Prkar1a-deficient mice." (PMID 26608815, 2015).
metastatic cancer (1 paper, 2020). A carcinoma which has spread from the original site of growth to another anatomic site. "MRNAs PRKCD, PRKAR1A, BTG2 competed with lncRNA RP11-408O19.5 for the same miRNAs (miR-15a-5p, miR-15b-5p, miR-16-5p, miR-195-5p) in primary cancer; lncRNA RP11-408O19.5 competed with GGA3 for miR-15b-5p, miR-16-5p, and miR-195-5p in metastatic cancer." (PMID 33614509, 2020).
myocardial hypertrophy (1 paper, 2020). "Therefore, it remains possible that PRKAR1A deficiency suppresses myocardial hypertrophy also through inhibition of Drp1 in vivo." (PMID 32212257, 2020).
Obesity (1 paper, 2020). Accumulation of substantial excess body fat. "This prompted us to look for genetic variants in GNAS, PDE4D, and PRKAR1A, and for methylation alterations of GNAS locus in a cohort of Finnish patients who had developed severe obesity already in early childhood." (PMID 32318528, 2020).
oligospermia (1 paper, 2012). Decreased number of spermatozoa in the semen. "Significantly, men with mutations in the PRKAR1A gene have reduced fertility due to defects in sperm morphology and azoo- or oligospermia." (PMID 23082183, 2012).
osteoporosis (1 paper, 2019). A condition of reduced bone mass, with decreased cortical thickness and a decrease in the number and size of the trabeculae of cancellous bone (but normal chemical composition), resulting in increased fracture incidence. "In addition to osteoporosis caused by PPNAD-associated cortisol hypersecretion, a PRKAR1A gene ablation has been reported to interfere with differentiation in osteoblastic cells, which may also lead to osteoporotic bone changes." (PMID 30915114, 2019).
ovarian cystadenoma (1 paper, 2019). A benign ovarian surface epithelial-stromal tumor characterized by the presence of cystic structures lined by serous epithelial cells, mucinous columnar epithelial cells, or endometrial-type well-differentiated cells. "Whole exome analysis was then performed on tissue from cardiac myxoma, brain metastasis, and ovarian cystadenoma revealing somatic mutations in PRKAR1A within the cardiac tumor and brain metastasis, but not in the tissue from the ovarian cystadenomas." (PMID 31874650, 2019).
pancreatic adenocarcinoma (1 paper, 2020). "Inactivating mutations of PRKAR1A in TC and, in less frequency, in pancreatic adenocarcinoma patients are associated with Carney Complex syndrome." (PMID 32443704, 2020).
parathyroid cancer (1 paper, 2022). "Additionally, four patients with parathyroid cancer had VUSs: two APC variants (c.5378C>G [p.Ala1793Gly] and c.890C>T [p.Thr297Ile]), one WT1 variant (c.1139G>A [p.Arg380Gln]), and one PRKAR1A variant (c.567A>C [p.Glu189As])." (PMID 35586626, 2022).
pituitary carcinoma (1 paper, 2017). A primary or metastatic malignant neoplasm affecting the pituitary gland. "Pituitary carcinomas rarely occur in genetic syndromes; examples of pituitary carcinoma patients with MEN1 mutations have been documented, whilst AIP, PRKAR1A, DICER1 and GPR101 mutations have not been associated with metastatic spread to date." (PMID 28284009, 2017).
preeclampsia (1 paper, 2017). Preeclampsia is a hypertensive disorder of pregnancy that is characterized by new-onset hypertension with proteinuria presenting after 20 weeks of gestation, and depending on mild or severe forms may initially present with severe headache, visual disturbances, and hyperreflexia. "In this study, GSTM2 and PRKAR1A were identified to be differentially regulated from the microarray in whole blood from women with preeclampsia and are an intrinsic part of this pathway." (PMID 28130428, 2017).
prostate carcinoma (1 paper, 2015). A carcinoma that arises from epithelial cells of the prostate gland. "PRKAR1A is functionally linked to AR during the progression of prostate cancer." (PMID 25915538, 2015).
Sepsis (1 paper, 2022). Sepsis is defined as life-threatening organ dysfunction caused by a dysregulated host response to infection. "In the meantime, the expression of PRKAR1A and PRKACB, which are negative regulators for MAPK pathway, was also decreased in the sepsis cohort, while the expression of the other 5 genes was not significantly altered." (PMID 35187084, 2022).
soft tissue tumors (1 paper, 2025). "Heterozygous knock-out of the PRKAR1A gene in mice leads to extracardiac myxomatous soft tissue tumors, in line with some of the CNC-associated tumors including cardiac myxomas." (PMID 39966109, 2025).
Spitz nevi (1 paper, 2022). "Complicating the matter, PRKAR1A-inactiated PEM have recently been found to harbor genomic anomalies associated with other melanocytic tumors, including Spitz tumors, therefore, PRKAR1A inactivation may be a secondary genetic event in a broad group of nevi, including Spitz nevi." (PMID 35747831, 2022).
synovial sarcoma (1 paper, 2022). "However, NGS brought forth mutations atypical for synovial sarcomas, including cAMP-dependent protein kinase type I-alpha regulatory subunit (PRKAR1A) on chromosome 17q24.2 and a likely pathogenic mutation of the neurofibromin 2 (NF2) gene on chromosome 22q." (PMID 36380356, 2022).
thyroid (1 paper, 2023). "In this comprehensive review, we aim to elucidate the intricate molecular mechanisms underlying thyroid tumorigenesis, specifically focusing on the deleterious consequences resulting from the deactivation of the PRKAR1A gene." (PMID 38074042, 2023).
type 2 diabetes mellitus (1 paper, 2021). A type of diabetes mellitus that is characterized by insulin resistance or desensitization and increased blood glucose levels. "However, it has been shown that PPARGC1A and PRKAR1A are changed in spermatozoa of type 2 diabetes mellitus patients." (PMID 34071734, 2021).